FGFR2 (fibroblast growth factor receptor 2)
Diseases named in the same sentence as FGFR2 in open-access papers (continued):
Sharing a sentence is not in itself a finding about the gene and the disease.
cancer (continued). "Given the recent clinical success of selective FGFR inhibitors, such as erdafitinib and pemigatinib, in FGFR-driven cancers, a systematic review of FGFR2 in GIST is both timely and necessary." (PMID 41150770, 2025). "FGFR2 fusion partners were several common genes such as BICC1 and TACC2, which are frequently detected in the biliary tract, while FGFR2 fusion partners of the other cancers were different from these common partner genes." (PMID 41226813, 2025). "In concordance with these findings, we observed earlier that inhibition of FGFR2 signaling effectively attenuates homology-mediated DNA repair in cancer cells and sensitizes them to DNA-damaging agents (e.g., DNA topoisomerase II inhibitor doxorubicin)." (PMID 41154409, 2025). "miR-16-1-3p and miR-16-2-3p, targeting the FGFR2 and decrease angiogenesis, cell migration, and neural outgrowth, and promote cancer metastasis in Osteosarcoma (OS) and thus their upregulation sensitizes the cells to radiotherapy." (PMID 40061926, 2025). "Another signaling molecule that has a key role in cancer progression is fibroblast growth factor receptor 2 (FGFR2)." (PMID 40061926, 2025). "The identification and detailed characterization of the FGFR2::SHTN1 fusion contribute significantly to the growing understanding of oncogenic gene fusions as potent drivers in human cancer." (PMID 41496852, 2025). "FGFR2 alterations in cancer can occur through various mechanisms, including gene amplification, point mutations, or protein overexpression." (PMID 40871637, 2025). "In 1312 cancers with FGFR2 abnormalities, FGFR2 amplification was detected in 515 cases (39.2%), fusion in 280 cases (20.9%), and mutation in 568 cases (43.3%)." (PMID 41226813, 2025). "This study revealed the distribution of FGFR2 abnormalities in some types of carcinomas and suggested the clinical usefulness of FGFR2 inhibitors for tumors with FGFR2 abnormalities not only fusion but also amplification and mutation." (PMID 41226813, 2025). "Analysis using large-scale genomic databases is important to clarify the significance of FGFR2 abnormalities in carcinomas." (PMID 41226813, 2025). "These compounds interfere with the kinase function of FGFR2, disrupting the cell signals essential for the cancer cells’ growth and persistence." (PMID 39195304, 2024). "In the following sections, we will delve deeper into the role of FGFR2 in GC, exploring its biological functions, its contribution to cancer pathogenesis, and the potential benefits and challenges of targeting FGFR2 as a therapeutic strategy." (PMID 39195304, 2024). "Conversely, FGFR2-positive cells were most abundant in precancerous (76.5%) and malignant tumors (52.2%), with lower levels in benign tumors (50.4%)." (PMID 39063983, 2024). "One study reported that FGFR2 is overexpressed in cancer tissues from patients with NPC and multiple NPC cell lines, and FGFR2 silencing enhances the effect of cisplatin treatment." (PMID 38918785, 2024). "The mean percentage of FGFR2-positive expression was 12.5% (SD = 34.2%) in normal histology, 76.5% (SD = 43.7%) in malignant tumors, 52.2% (SD = 50%) in precancerous lesions, and 50.4% (SD = 50.2%) in benign tumors." (PMID 39063983, 2024). "FGFR2 belongs to the FGFR family of receptor tyrosine kinases of which members were found to be fused to a variety of translocation partners in multiple cancers." (PMID 38391914, 2024). "In contrast, FGFR2 was significantly elevated in precancerous and malignant tumors, indicating its role in the progression and aggressiveness of cSCC." (PMID 39063983, 2024). "The reduction in TRPA1 levels stops the activation of the fibroblast growth factor receptor 2 (FGFR2), preventing the spread of cancer cells to the brain." (PMID 39408656, 2024).
cancer (continued). "HER2 alterations (point mutations or increased expression) occurred with similar frequencies in samples with activating mutations in receptor tyrosine kinases FGFR2/3, in tumors with RAS/RAF gene mutations, and in FGFR2/3- and RAS/RAF-wild type carcinomas." (PMID 39596194, 2024). "Patients with higher FGFR2 levels had higher survival rates, and were more likely to have ER+ carcinomas." (PMID 39596875, 2024). "Genomic alterations in gene coding for FGFRs are rare in EG cancers, ranging between 3 to 10% of the cases in different series and mainly represented by amplifications or rearrangements of the FGFR2 gene." (PMID 36983691, 2023). "Among ICC patients, only 1.38% (4/290) exhibited FGFR2 mutations, with FGFR2 in-frame deletions being more prevalent in ICC compared to other cancer types." (PMID 37964396, 2023). "Previous studies have demonstrated the importance of FGFR2 for cell migration, invasion, growth and cancer progression in CRC, with gene amplification being reported in primary CRC, and expression being associated with poor survival." (PMID 36890818, 2023). "Exemplary cases include ncORFs in the cancer hallmark genes CREBBP, CRTC1, CSF3R, FGFR2, IKZF1 and MAP2K2 with peptide support in all but two of the analyzed cancer types." (PMID 37275273, 2023). "FGFR2 amplification is less frequent than FGFR1 amplification across cancer types and is most often reported in patients with gastric-oesophageal junction adenocarcinoma and breast cancer." (PMID 37493315, 2023). "A previous study has shown that ESRP1/2 induces the shift from the epithelial splice form of FGFR2 IIIb to the mesenchymal splice form of FGFR2 IIIc, which is important for cancer cell invasion and metastasis." (PMID 37090731, 2023). "Fgf9 from tuft cells is predicted to target Fgfr1 on fibroblasts in both PRN and PRT, and epithelial cells through Fgfr1 or Fgfr2 in PRT cancer model." (PMID 37386128, 2023). "The newly identified genes included several well-known cancer drivers, such as Fgfr2, Hras, Tgfbr2, Nf1, and Erbb2, as well as others whose function in cancer remains elusive." (PMID 37063417, 2023). "FGFR2 amplification is present in approximately 5 to 10% of GC cases, with a higher percentage in scirrhous cancer." (PMID 37834127, 2023). "A significant association of the FGFR2 rs1219648 variant with BC risk was found for the HER2 (+) status, grade 2 cancer, and positive lymph node status of patients." (PMID 37107577, 2023). "Oncogenic FGFR fusions have been identified in several cancers, in which FGFR2 and FGFR3 fusions are mostly observed." (PMID 37493315, 2023). "Multicenter and pan-cancer studies demonstrated that FGFR2 in-frame deletions were more prevalent in ICCs (0.62%) than in other cancers, and were not limited to the extracellular domain." (PMID 37964396, 2023). "The first group of genes was well-known cancer-related genes, i.e., Fgfr2, Hras, Tgfbr2, Nf1, and Erbb2." (PMID 37063417, 2023). "What percentage of FGFR2-expressing cancer cells is needed to make a conclusion about FGFR2-positivity?" (PMID 38155920, 2023). "By characterizing the distinct FGFR2 genetic alterations in multiple centers and pan-cancer studies, we aimed to determine the prevalence of different FGFR2 genetic alterations in our population." (PMID 37964396, 2023). "PHLDA1 negatively regulates Akt in the context of FGFR2, whereas loss of PHLDA1 expression contributes to cancer cell survival and FGFRi resistance due to reactivation of Akt." (PMID 37225844, 2023). "In the context of cancer, aberrant signalling of FGF10 through FGFR2 IIIb, and to a lesser extent FGFR1 IIIb, has been implicated in a range of cancers." (PMID 37130917, 2023). "Five genes were implicated in the development of other cancer types: SRGAP2C, MAP3K1, FGFR2, LSP1, and FMNL3." (PMID 36703164, 2023). "All of these FGFs bind to FGF receptor 2 (FGFR2), deregulation of which has been observed in many types of cancer." (PMID 36937440, 2023).
cancer (continued). "It is also relevant that the poorly treatable and aggressive subtype of diffuse carcinomas (poorly cohesive carcinomas) shows FGFR2 amplification." (PMID 36416959, 2023). "Based on our results, we believe that the primary TMA we used, considering more than 800 samples from carcinoma patients, provided realistic results despite relevant heterogeneity of FGFR2 amplification." (PMID 36416959, 2023). "On the basis of these correlates, we obtained the human SUM52PE, MFM-223, SNU-16, KATO-III and NCI-H716 cancer cell lines, each expressing amplified FGFR2 variants." (PMID 35948633, 2022). "FGFR2 amplification and fusion were identified in approximately 1.5% and 1.1% of all cancer types in 1,373 patients, respectively, with both FGFR2 amplification and fusion occurring together at a rate of approximately 0.6%." (PMID 35342406, 2022). "Although there was a relatively weak correlation between FGFR2 genetic alteration and the biomarker PD-L1, the blockade of FGFR2 aberrations in human cancers is considered to be a promising approach for targeted therapy." (PMID 35342406, 2022). "Accurate characterization of HER2 and FGFR2 expression in specific types of cancer is important for determining the relevance of these proteins as markers for identifying potential candidates for treatment with relevant targeted therapies." (PMID 35585358, 2022). "Fibroblast growth factor receptor 2 (FGFR2) is a tyrosine kinase that is involved in cancer pathogenesis." (PMID 35311468, 2022). "FGFR2 is a receptor for fibroblast growth factors, and it is oncogenically activated by genetic alterations in cancer." (PMID 35954414, 2022). "A single treated mouse developed a lung tumor and was found to have an rAAV integration in fibroblast growth factor receptor 2 (Fgfr2), a gene known to show altered expression in some cancers." (PMID 35690906, 2022). "Alofanib (RPT-835) is the unique selective allosteric FGFR2 inhibitor developed for cancer treatment." (PMID 35054474, 2022). "The proportions of FGFR2ΔE18, FGFR2amp and FGFR2hotspot varied across cancer entities, suggesting differential selections of FGFR2 aberrations and concurrent driver alterations among tissues of origin." (PMID 35948633, 2022). "FGFR-2 plays an important role in cancer progress even if via the epithelial-mesenchymal transition." (PMID 35885641, 2022). "In this study, we showed that the rate of FGFR2 gene amplification was higher in GC than in other types of cancer, consistent with previous studies indicating an incidence of FGFR2 amplification in GC of approximately 1.3%." (PMID 35342406, 2022). "FGFR2 fusions are the result of gene rearrangements and have been observed in different types of cancer with different incidence per cancer type." (PMID 35342406, 2022). "To examine possible cooperation between FGFR2 variants and other genes, we analysed driver gene alterations diagnosed by FMI oncogenomic profiling and their incidence in FGFR2-altered cancers." (PMID 35948633, 2022). "The LLPS-related genes involve in multiple cancer-related pathways, such as FGFR2 alternative splicing and mRNA splicing." (PMID 36193491, 2022). "In the TCGA cohort of 285 cancer patients that underwent comprehensive RNA-seq5, only one patient (0.35%) was found to carry a FGFR2 fusion." (PMID 36369474, 2022). "Truncation of exon 18 of FGFR2 (FGFR2ΔE18) is a potent driver mutation in mice and humans, and FGFR-targeted therapy should be considered for patients with cancer expressing stable FGFR2ΔE18 variants." (PMID 35948633, 2022). "The AS transcripts of cancer hallmarks genes like FGFR2 showed differential rhythmicity unique to HCT116_ARNTLKO." (PMID 35552415, 2022).
cancer (continued). "It is also shown that FGFR2 positively regulates PD‐L1 and that a combination of FGFR2 inhibition and immune checkpoint blockade kills cancer cells." (PMID 34514747, 2021). "FGFR2/CEN10 ratio of cancer cells with FGFR2IIIb and/or FGFR2IIIc overexpression was significantly (p < 0.01) correlated to that of IHC score by immunohistochemical staining." (PMID 33633310, 2021). "Owing to its important role in tumorigenesis, FGFR2 has recently been considered a critical therapeutic target for cancer." (PMID 33968743, 2021). "In general, these findings highlight the critical role of FGFR2 in oncogenesis and provide a potential therapeutic target for cancers." (PMID 33968743, 2021). "In contrast to FGFR1 amplification and FGFR3 mutation, research has shown that the response to AZD4547 among FGFR2-amplified cancers is strong." (PMID 34639155, 2021). "LLC2B-Cy5.5 binding to FGFR2-positive cancer cells was confirmed by fluorescent microscopic imaging and flow cytometry in vitro." (PMID 34440055, 2021). "Knockdown or inhibition of either FGFR1 or FGFR2 limits the ability of pancreatic cancer cells to form spheroids, a characteristic of cancer stem cells, suggesting an involvement of FGF signalling in maintaining stemness." (PMID 33918004, 2021). "Several FGFR2 inhibitors have been developed for the treatment of cancer patients with enhanced expression of FGFR2 signaling." (PMID 33633310, 2021). "First, we compared the mRNA expression profiles of FGFR2 between tumors and the corresponding normal tissues of various cancer types by GEPIA2." (PMID 33968743, 2021). "The FGFR2 expression analysis obtained here needed to be validated with more samples for each individual cancer types in the future." (PMID 33968743, 2021). "We first explored the clinical significance of FGFR2 expression, and the association between FGFR2 mRNA expression and patient overall survival (OS) and progression-free survival (PFS) in individual cancer types was analyzed." (PMID 33968743, 2021). "Conversely, certain cancer types, including OV, PCPG, ESCA, and PAAD, mainly harbor FGFR2 amplification but rarely mutations." (PMID 33968743, 2021). "Based on the TCGA Fusion Gene Database, we detected fusion transcripts of FGFR2 across different cancer types with high confidence." (PMID 33968743, 2021). "Recently, with the use of whole‐exome sequencing and fluorescence in situ hybridization, multiple FGFR2 chromosome fusions with genomic partners in some cancers, including ICC, have been identified." (PMID 33277810, 2021). "Aprutumab ixadotin (BAY 1187982) is a novel antibody-drug conjugate (ADC) that has shown preclinical efficacy against FGFR2-mutant cancer cell lines." (PMID 34068816, 2021). "Previous studies on FGFR2 expression in cancer have used several different research methods and are limited to small sample sizes and/or to single or limited numbers of cancer types." (PMID 33968743, 2021). "In the presence of CAFs, expression of FGF4 and FGFR2 is increased in cancer stem cells isolated from the ovarian cancer cell line HTBoA." (PMID 34068954, 2021). "In this study, we profiled 32 cancer types regarding FGFR2 expression, methylation, alteration and their clinical associations." (PMID 33968743, 2021). "One study found subjects with dental agenesis had a major chance of family history of cancer and associations with AXIN2, FGF3, FGF10, and FGFR2 genes." (PMID 34378652, 2021). "FGFR2 is one of the receptors for fibroblast growth factor, and has been shown to be activated in a number of cancers through a variety of mechanisms, including gene amplification, translocations, and point mutations." (PMID 33450701, 2021). "In HER2-positive GC, miR-494 inhibits cancer-initiating cell phenotypes and reverses resistance to lapatinib by reducing the expression of fibroblast growth factor receptor 2 (FGFR2)." (PMID 34966746, 2021).
cancer (continued). "While FGFR1-4 alterations have been described in many cancers, FGFR2 fusions are particularly enriched in iCCA, occurring in 5–15% of cases, although there have been reports as high as 45%." (PMID 33916849, 2021). "In our study, the FGFR2 profiles were mainly analyzed by the cBioportal approach, which would unify the TCGA data across different cancer types with uniform clinical elements and ideally processed curation." (PMID 33968743, 2021). "The FGFR2 alteration (mutation and CNV) frequency in all TCGA cancer types was ~3.3% (360 of 10,953 patients, 360 of 10,967 samples)." (PMID 33968743, 2021). "In further support of a use for ponatinib in FGFR driven cancers, a clinical trial using ponatinib to treat patients with advanced biliary cancer that express FGFR2 fusions has recently been run." (PMID 33918004, 2021). "The motivation is to better comprehend the molecular responses to FGFR2 activation in cancer and identify new biomarkers and targets for more effective use of agents directed at inhibition of FGFR2 signalling." (PMID 32409632, 2020). "The median cancer-specific survival interval for patients carrying FGFR2 translocations was significantly longer (123 months) than that for patients without FGFR2 translocations (37 months, P = 0.039)." (PMID 32962091, 2020). "These properties allow peptides to be excellent candidates for cancer‐targeted therapy, such as FGFR2 inhibitors." (PMID 34766128, 2020). "FGFR2 amplification is less frequent (0.34%) and has been described in some cancer types, including breast, gastric, and esophageal carcinoma." (PMID 32962091, 2020). "Further conditioned medium (CM) from MC38 cancer cells was sufficient to induce Fgfr1 and Fgfr2 although with a longer time course." (PMID 32792542, 2020). "In cancer cells, genetic and epigenetic modifications of FGFR2 lead to overexpression, fusion protein, and increased ligand-binding affinity." (PMID 32934314, 2020). "In summary, our data confirmed co-expression of PLAC1 and FGFR2 in both the placental syncytiotrophoblast and in human cancer cell lines, and demonstrated that PLAC1 is a secreted protein, which accumulates in the ECM." (PMID 32499871, 2020). "Recent studies also identified aberrant FGFR2 signalling as an important factor in oncogenesis and as a potential drug target in different cancer types." (PMID 32522271, 2020). "Recently, an anti-FGFR2 antibody has been approved as a second-line treatment option in iCCA, and it is the first targeted therapy for this cancer." (PMID 32781527, 2020). "As the first step toward this study, we confirmed FGFR2 expression in different cancer cell lines by using both QPCR and Western blotting." (PMID 34766128, 2020). "This amplification is targetable with high sensitivity to FGFR inhibitors in vitro, an FGFR2-targeting antibody showed potent antitumor activity against human cancers in pre-clinical studies and several FGFR tyrosine-kinase inhibitors are in clinical trials." (PMID 32793490, 2020). "For instance, G-Rh2 induces the apoptosis of cancer cells by inhibiting FGFR2, CSF1R, EGFR, and LYN." (PMID 33488754, 2020). "Recent reports suggest that fibroblast growth factor receptor 2 (FGFR2) expressing cancer cells, which have a low abundance of the protein Gbr2, show a high abundance for metastasis." (PMID 33329751, 2020). "FGFR2 has been proposed as a target for cancer therapy, because both the expression and activation of FGFR2 are boosted in various malignant carcinomas." (PMID 34766128, 2020). "FGFR2 is overexpressed on many different kinds of cancer cells and is crucial for their proliferation." (PMID 34766128, 2020). "Our results highlight that both DcP5 and P5 are potential anticancer agents and cancer‐targeted peptides for FGFR2‐overexpressed malignancies." (PMID 34766128, 2020). "The results indicated that FGFR2 is widely expressed in various cancer cells, suggesting FGFR2 as a target for drug design." (PMID 34766128, 2020).